GSK3B-DT (GSK3B divergent transcript)
Synonyms: GPNCA
Gene: Long non-coding RNA gene on chromosome 3 (120,094,737 to 120,185,702, forward strand). Ensembl gene ENSG00000242622.
Diseases named in the same sentence as GSK3B-DT in open-access papers:
GSK3B-DT is named in the same sentence as 11 diseases in open-access papers, as found by Europe PMC text mining. Sharing a sentence is not in itself a finding about the gene and the disease.
GSK3B-DT shares sentences with these, for which no sentence is quoted: breast carcinoma (1 paper); cancer (1); colon cancer (1); liver cancer (1); lung adenocarcinoma (1); lung squamous cell carcinoma (1); prostate carcinoma (1); renal carcinoma (1); renal clear cell cancer (1); stomach adenocarcinoma (1); tumor (1).